ERCC1 (ERCC excision repair 1, endonuclease non-catalytic subunit)
Diseases named in the same sentence as ERCC1 in open-access papers (continued):
Sharing a sentence is not in itself a finding about the gene and the disease.
cancer (continued). "Emodin at a concentration of 20 μg/mL in MCF-7/Adr cells significantly decreased excision repair cross complementation group 1 (ERCC1) expression, which can lead to multi-drug resistance to chemotherapy in cancer treatment." (PMID 34073059, 2021). "ERCC1 overexpression is found in many different types of cisplatin-resistant cancers, such as HNSCC, bladder, and lung cancers." (PMID 34360968, 2021). "Positivity of protein marker expression for all cancers combined was: ERCC1 20.9%, MGMT 55.4%, RRM1 19.9%, TOPO1 58.7%, TOP2A 75.8%, TS 34.0% and TUBB3 56.8%." (PMID 31479512, 2020). "Several reports suggest that alternative splicing of specific genes, such as BRCA1, BRCA2, BARD1, or ERCC1, can impact on the response of cancer cells to PT and some studies also suggest that this correlates with PT resistance in human cancer." (PMID 32332923, 2020). "Inversely, the inhibition of ERCC1–XPF complex would sensitize cancer cells to cisplatin and other regiemens whose effect requires ERCC1–XPF repair activity." (PMID 33266377, 2020). "Studies have demonstrated that low expression of ERCC1 within the tumors improves the response to chemotherapy based on cisplatin and the outcome of cancer by decreasing the removal of cisplatin- induced DNA adducts resulting in increased survival." (PMID 32922493, 2020). "Owing to the important role of the ERCC1/XPF complex in the DNA repair process, exploring the role of ERCC1/XPF gene polymorphisms in cancer risk has been a major focus of research." (PMID 33067872, 2020). "Excision repair cross-complementing 1 (ERCC1) is a protein that has been related to response to platinum-based chemotherapy in multiple cancer types." (PMID 33266377, 2020). "ERCC1 has been demonstrated to be an independent prognostic marker in PCa and a therapeutic target to sensitize cancer cells to chemotherapy." (PMID 33014785, 2020). "The literature data presented above show a significant relationship between the ERCC1 expression and survival in different types of cancer." (PMID 32397531, 2020). "Previous studies have also reported a relationship between ERCC1/XPF gene polymorphisms and cancer risk." (PMID 33067872, 2020). "Recent studies suggest that the resistance to platinum drugs in cancer is related to high ERCC1 expression." (PMID 33014113, 2020). "The results showed that the gene expression of ERCC1 in carcinoma tissue (0.67 ± 0.29) was significantly higher than that in corresponding normal pericarcinomatous tissue (0.27 ± 0.13, P = 0.001) of OSCC patients." (PMID 33029487, 2020). "In this study, we showed that the ERCC1 mRNA level was significantly increased in OSCC carcinoma tissue as compared to the corresponding normal pericarcinomatous tissue." (PMID 33029487, 2020). "In this study, we examined the gene expression of ERCC1 in the carcinoma tissue and corresponding normal pericarcinomatous tissue of OSCC patients using real-time PCR." (PMID 33029487, 2020). "A total of 13 SNPs in ERCC5, ERCC2, ERCC1, XPC, and XPA genes, which have been found to affect the risk and/or survival of cancers, were selected in the present study." (PMID 30609649, 2019). "GT type of ERCC1 and AA type of XRCC1 were associated with distal location of the cancer (p=0.018) and female gender (p=0.043), respectively." (PMID 31602266, 2019). "Many studies have assessed the predictive value of ERCC1 in patients with cancer receiving CDDP-based therapies." (PMID 31450627, 2019). "Overexpression of ERCC1 in cancer cells clears the cisplatin-induced DNA adducts, and brings about the drug resistance." (PMID 30563166, 2018). "Rare and possibly damaging variants were identified in 12 candidate genes in this cohort, including variants in DNA repair genes (ERCC1 and SXL4) and other cancer-related genes (NOTCH2, ERBB2, MST1R, and RAF1)." (PMID 29868112, 2018).
cancer (continued). "Others reported expression of ERCC1, which was relative to cisplatin-based chemotherapy resistance in cancers, was higher in the WHO type IIa compared with WHO type IIb8,26." (PMID 30190563, 2018). "Although its activity is required to maintain genome integrity in healthy cells, ERCC1-XPF can counteract the effect of DNA-damaging therapies such as platinum-based chemotherapy in cancer cells." (PMID 29710850, 2018). "Previous research pointed out that coadministration with curcumin and cisplatin on cancer cells increased cytotoxicity to cisplatin, and was mediated by down-regulation of the expression levels of TP and ERCC1 and by inactivation of ERK1/2." (PMID 30563166, 2018). "ERCC1 expression levels determined the sensitivity of cells to Pt in part, and LRP expression was associated with resistance to anti-cancer drugs including cisplatin, carboplatin, doxorubicin, etoposide and paclitaxel in vitro." (PMID 28484093, 2017). "While this work was being carried out, another study reported that expression of the XPF-interacting domain of ERCC1 in cancer cells resulted in increased sensitivity to DNA damaging agents, but without any investigation of the mechanism involved." (PMID 28903417, 2017). "Overexpression of ERCC1 has been found in many cancer types such as urothelial carcinoma, head and neck squamous cell carcinoma and non-small cell lung cancer." (PMID 28747165, 2017). "At least weak ERCC1 staining was found in 85.4% of cancers with immunohistochemically detected ERG expression and in 81.4% of tumors with ERG-rearrangement, but only in 52.6% (IHC) or 61.8% (FISH) of ERG-negative cancers (p < 0.0001 each)." (PMID 28747165, 2017). "A further refined subgroup analysis by quantitative Gleason grading showed that high ERCC1 expression identified cancers with worse outcome only in those 3 + 4 carcinomas with a minimal fraction of Gleason 4 (≤5%) (p = 0.0004)." (PMID 28747165, 2017). "The fact that EC aerosols used in this study, like MS smoke, can lead to a significant decrease in the expression of ERCC1 and OGG1, suggest yet another mechanism by which exposure to EC aerosol can contribute to DNA damage, and therefore increase cancer risk." (PMID 28542301, 2017). "The expression of four MMR genes and ERCC1 were assessed by immunohistochemistry (IHC) from cancer tissue samples of 2233 consecutive CRC patients." (PMID 28767665, 2017). "The PFS of patients with ERCC1-low cancer was 242 days, compared with 135 days for ERCC1-high patients (P = .032)." (PMID 29390553, 2017). "The association between deletions and ERCC1 expression was less clear in ERG positive than in ERG-negative cancers, which is likely due to the (already) markedly elevated levels of ERCC1 in ERG-positive tumors." (PMID 28747165, 2017). "Pre-clinical studies have suggested that underexpression of ERCC1 sensitizes cancer cells to platinum agents whereas overexpression induces resistance." (PMID 27888622, 2017). "Further development of ERCC1-XPF DNA repair inhibitors is expected to sensitize cancer cells to DNA damage-based chemotherapy." (PMID 27650543, 2016). "After TRF2 inhibition, a partial loss of telomeric G-strand overhangs was observed that was dependent on ERCC1-XPF nuclease and overexpression of TRF2 led to XPF-dependent telomere loss, increased DNA damage, aging and cancer in mouse keratinocytes." (PMID 27228173, 2016). "We have shown that targeting ERCC1 and XPF individually or targeting the ERCC1-XPF complex can significantly enhance cytotoxicity in cancer cell lines." (PMID 27650543, 2016). "Linkage disequilibrium-mapping studies in Caucasians have indicated anassociation of Chr19q13.3 sub-region spanning ERCC2, PPP1R13L, CD3EAP and ERCC1 with several cancers." (PMID 27183913, 2016).
cancer (continued). "Based on the biological significance of ERCC1, its use as a predictive or prognostic biomarker has been pursued by a large number of cancer researchers." (PMID 26056042, 2015). "The aim of the present study was to test for any association between the ERCC1 and ERCC2 gene variants and three different types of cancer in Mexican-mestizo patients." (PMID 25789018, 2015). "Allele and genotype frequencies of Asn118Asn (ERCC1) and rs13181 (ERCC2) were distributed according to the HWE model in each group in all types of cancer (P>0.05)." (PMID 25789018, 2015). "For ERCC1 there was a slight trend toward worse OS with high expression in both pan-cancer and mCRC cohorts, the magnitude of which was exaggerated in patients treated with platinum chemotherapy." (PMID 26083491, 2015). "Mutations in genes of the NER pathway, including xeroderma pigmentosum group C (XPC) and excision repair cross complementation group 1 (ERCC1), are associated with elevated risk for various cancers." (PMID 26404324, 2015). "We also need to elucidate the molecular mechanisms underlying the confounding effects of ERCC1 and DPYD gene expression in cancer cells." (PMID 26372896, 2015). "The Asn118Asn (rs11615) variant in the ERCC1 gene, and the Lys751Gln (rs13181) and Asp312Asn (rs1799793) variants in the ERCC2 gene have been associated with the development of varied types of cancer." (PMID 25789018, 2015). "Excision repair cross-complementing gene 1 (ERCC1) is a member of the exonuclease repair enzyme family, and its low expression is always related with elevated cancer incidence while its high expression is always related with resistance to platinum drugs." (PMID 24502441, 2014). "ERCC1 is a member of the exonuclease repair enzyme family and its low expression is always related to elevated cancer incidence, while its high expression is always related to resistance to platinum drugs." (PMID 24502441, 2014). "For example, the aberrant regulation of ERCC1, TYMS, TUBB3, RRM1 and TOP2A is associated with the abnormal proliferation of cancer cells, according to the hallmarks of cancer that were proposed previously." (PMID 24926347, 2014). "The knockdown of ERCC1 and XPF protein levels by RNA interference increased sensitivity of cancer cells to oxaliplatin; overexpression of exogenous ERCC1 significantly decreased drug sensitivity." (PMID 23982883, 2014). "Several clinical studies have explored the role of ERCC1 as a marker for platinum sensitivity in cancer patients." (PMID 25253066, 2014). "Recent studies have confirmed that ERCC1 is the key enzyme of the DNA repair induced by cisplatin and it has been shown that ERCC1 expression of some malignant tumors played an important role in guiding chemotherapy." (PMID 24502441, 2014). "We performed Western immunoblot analysis to evaluate the expression level of PAR, FancD2, and ERCC1, in the human cancer cell lines H1299 following exposure to veliparib." (PMID 25566506, 2014). "The vast majority of nodes evaluated in regions adjacent the primary tumor location in all patients were assigned values of either 0 or 1 (ERCC1− = 81.5%, ERCC1+ = 83.9%) suggesting limited nodal cancer spread and development." (PMID 25191856, 2014). "Repair proteins, such as ERCC1 are therefore important for cancer cells resistance to platinum and other DNA-targeting or altering therapeutics." (PMID 25191856, 2014). "Polymorphisms in the excision repair cross-complimentary group 1 (ERCC1) gene have been involved in the prognosis of various cancers." (PMID 25253066, 2014). "Quantitative measurement of three independent patient samples demonstrated a significant enhancement of β-tubulin III and ERCC1 staining in cancer cells surviving paclitaxel treatment in vitro, compared to their matched control counterparts." (PMID 24886434, 2014). "Considering gene-gene interaction analysis, we found a significant joint effect of ERCC1 –399Gln and PARP-1–762Ala on increased cancer risk in a homozygous genetic model." (PMID 24853559, 2014).
cancer (continued). "Although both excision repair cross-complementing group 1 (ERCC1) and breast cancer susceptibility gene 1 (BRCA1) can be effective biomarkers for chemosensitivity in primary malignant tumors, their applicability to metastases is poorly understood." (PMID 23496813, 2013). "Elevated mRNA levels of excision repair cross-complementation group 1 (ERCC1) are reported in clinical resistance to platinum-based chemotherapy for various cancers." (PMID 24351910, 2013). "Excision repair cross-complementing 1 (ERCC1) is reported to be involved in the sensitivity of cancer cells to platinum-based chemotherapy." (PMID 23426424, 2013). "For let-7e-3p, cancer-associated genes such as MAPK1 and EZH2 were among the negatively correlated genes, and PURA, ERCC1 and MAPT were among the positively correlated ones." (PMID 24257477, 2013). "The mechanisms whereby ERCC1 participates in platinum resistance in cancer cells has been demonstrated to be correlated with increased removal of the platinum-DNA adducts and interstrand cross-links." (PMID 23426424, 2013). "At different points of time, the positive rates of ERCC1 expression in residual carcinoma were detected by immunohistochemistry." (PMID 24345485, 2013). "Comparing with the control group, the positive rate of ERCC1 expression in residual carcinoma in RFA group increases transiently within 1 d to 5 d (53.7%±1.6% & 32.9%±2.5%), and 5 d later, it decline to the level of the control group." (PMID 24345485, 2013). "Expression of ERCC1 proteins was assessed by immunohistochemistry, and expression of the ERCC1 proteins was detected in the nuclei of cancer cells." (PMID 22439756, 2012). "Overall, substantial deficiencies in protein expression of DNA repair proteins Pms2, Ercc1 and Xpf frequently occur in a coordinated manner in extensive regions, involving as many as 1 million crypts, near cancers, and also occur within cancers." (PMID 22494821, 2012). "Thus, it is possible that functional ERCC1 variants may also play a role in cancer risk." (PMID 23166636, 2012). "We observed that cancers frequently had areas with restored expression of Pms2, Ercc1 and/or Xpf, even though surrounding areas of the cancers had reduced levels of Pms2, Ercc1 and/or Xpf." (PMID 22494821, 2012). "The NER system represented by ERCC1 is extensively involved in human cell DNA repair after damage, but over-expression of ERCC1 can lead to multi-drug resistance to chemotherapy in cancer treatment." (PMID 23046742, 2012). "Clinical studies have shown that the level of ERCC1 gene expression in cancer patients is correlated to drug resistance of cisplatin-based chemotherapy." (PMID 23171216, 2012). "First, siRNAs designed to block ERCC1 expression were used to deplete two epithelial carcinoma cell lines (including one NSCLC cell line) of ERCC1 protein." (PMID 21152077, 2010). "In a study involving four cancer cell lines, ovarian and an inherently cisplatin-resistant colon (HT-29), ERCC1 mRNA levels measured after exposure to oxaliplatin for 20 hours were higher than in the control—the A2780 (ovarian) cell line." (PMID 22276017, 2009). "Two additional pharmacogenomic-directed trials in patients with NSCL cancer are evaluating the predictive value of ERCC1 status in relation to adjuvant cisplatin-gemcitabine (SWOG) or erlotinib with or without cisplatin (IFCT) therapy." (PMID 22275966, 2008). "Many reports have explored the role of the excision repair cross-complementation group 1 enzyme (ERCC1) expression in the repair mechanism of cisplatin-induced DNA adducts in cancer cells." (PMID 19578506, 2008). "While our findings showed no OS association with ERCC1 rs11615 and rs3212986, these SNPs have been widely studied in various cancers with varying survival outcomes." (PMID 40526606, 2025). "Therefore, both type I PRMT and PRMT5 inhibitor treatments significantly repressed ERCC1 expression and activity levels in cancer cells." (PMID 38826355, 2025).
cancer (continued). "ERCC1 is a valuable biomarker for platinum-based chemotherapy in cancer." (PMID 39192988, 2024). "Notably, ERCC1 showed higher expression in cancer tissues than in normal tissues in all cancer types, whereas ERCC4 showed lower expression in cancer tissues than in normal tissues only in KIRC, KIRP, PRAD, THCA, and UCEC." (PMID 39192988, 2024). "Consequently, recent research has explored inhibiting the interaction between the ERCC1/XPF complex in cancer cells to make them more vulnerable to platinum-based therapy." (PMID 39051064, 2024). "It was observed that ERCC1 exhibited higher expression in cancer compared to the other genes." (PMID 39192988, 2024). "The algorithm implemented in this study expands our comprehension of chemotherapeutic resistance and how to overcome it through identifying ERCC1/XPF inhibitors with the aim of enhancing chemotherapeutic impact giving hope for ameliorated cancer treatment outcomes." (PMID 39051064, 2024). "Biomarker analysis has suggested that DNA damage response markers, such as MRE11 and ERCC1/2, may predict cancer-specific survival among two independent TMT cohorts." (PMID 37641150, 2023). "Polymorphisms in ERCC1 and ERCC2 could alter the ability to repair DNA, thereby affecting the response or survival of cancer patients." (PMID 36980706, 2023). "The overexpression of ERCC1 in cancer patients might increase the effectiveness of chemotherapy and radiotherapy through the DNA repair of ERCC1." (PMID 37296596, 2023). "In addition, in the treatment environment of radiation and chemotherapy drugs, ERCC1 was produced via cancer cells immediately." (PMID 37296596, 2023). "Therefore, investigating the role of ERCC1 expression in cancer has always been the focus of research." (PMID 36338712, 2022). "The aim of the pan-cancers analysis was to study the effect of ERCC1 expression on immune responses to identify patients with different types of cancers that may benefit from anti-ERCC1 immunotherapy." (PMID 36338712, 2022). "However, no negative correlation was observed between immunomodulators or immune checkpoints and ERCC1 expression in patients with other cancers such as LGG, LAML, BLCA, and KIPAN." (PMID 36338712, 2022). "Further, a correlation between ERCC1 expression and chemoresistance in cancer also exists." (PMID 36338712, 2022). "In this study, we first analyze the ERCC1 expression and the prognosis of patients with pan-cancer." (PMID 36338712, 2022). "Polymorphisms in the ERCC1 and XPC genes may influence the genomic stability then modify the disease risk, especially cancers." (PMID 35693108, 2022). "We suggest that, although prognostic value of ERCC1 expression strongly depends on treatment regimen and disease characteristics in BC, it still represents a valuable factor in designing of prognosis scoring algorithm/cancer treatment algorithm." (PMID 36293346, 2022). "The previous study showed that the rs3212986 polymorphism of ERCC1 has been associated with better objective response to chemotherapy among Asian patients with cancer, while studies on Caucasians have not found a significant association." (PMID 36712419, 2022). "Indeed, ERCC1 depletion in cancer cells resulted in lower nicotinamide adenine dinucleotide phosphate hydrogen (NADPH), NADP+, NADH and NAD+ levels." (PMID 36232946, 2022). "ERCC1 can also affect the sensitivity of cancer to chemotherapy with platinum-based drugs." (PMID 36497451, 2022). "ERCC1 plays a critical role in the repair of platinum-induced DNA damage and has been reported as a negative predictive marker for response to platinum treatment in various cancer types." (PMID 33671266, 2021). "As there are many SNPs in the ERCC1 gene and only a few SNPs may contribute to the occurrence of cancer, it is extremely important to choose the right candidate polymorphisms to test an association with OSCC." (PMID 33029487, 2020).